EGFR (epidermal growth factor receptor)
Diseases named in the same sentence as EGFR in open-access papers (continued):
Sharing a sentence is not in itself a finding about the gene and the disease.
non-small cell lung carcinoma (continued). "Roughly one third of non-small cell lung cancer (NSCLC) patients with epidermal growth factor receptor tyrosine kinase inhibitor (EGFR-TKI)-sensitive mutated (EGFRm) tumors experience disease progression through central nervous system (CNS) metastases during treatment." (PMID 34630120, 2021). "The EGFR N771delinsGY mutation has been reported in non-small cell lung cancer." (PMID 33048186, 2021). "As a third-generation EGFR tyrosine kinase inhibitor (TKI), osimertinib is approved for treating advanced non-small cell lung cancer (NSCLC) patients with EGFR-T790M mutation after progression on first- or second-generation EGFR-TKIs such as gefitinib, erlotinib and afatinib." (PMID 34660285, 2021). "Characterization of aberrant oncogenic signaling in non-small-cell lung cancer (NSCLC) has resulted in precision cancer medicine treatment approaches via tyrosine kinase inhibitors (TKIs) towards mutated epidermal growth-factor receptor (EGFR) or EML4-ALK fusions." (PMID 33671772, 2021). "For instance, the top identified gene associated with non-small cell lung cancer is EGFR." (PMID 34575089, 2021). "The analysis of cfDNA mutations has already been introduced in the guidelines of non-small cell lung cancer management where secondary EGFR mutation T790M is being followed for early detection of acquired resistance to first-line EGFR-tyrosine-kinase-inhibitors." (PMID 33669856, 2021). "Combining radiomic phenotypes, ctDNA, and clinical variables may enhance precision oncology approaches to managing advanced non-small cell lung cancer with EGFR mutations." (PMID 33976268, 2021). "Well established examples include KIT mutations which are present in ~ 85% of gastro-intestinal stromal tumors, EGFR mutations that have been identified in ~ 15% of non-small cell lung cancers, and lung and colorectal cancers with mutations in the KRAS oncogene." (PMID 32087721, 2020). "Furthermore, afatinib and osimertinib have recently been approved for the treatment of EGFR mutated non-small cell lung cancers, while the combination of BRAF and MEK inhibitors improve overall survival in melanoma." (PMID 32087721, 2020). "Epidermal growth factor receptor EGFR major driver mutations may affect downstream molecular networks and pathways, which would influence treatment outcomes of non-small cell lung cancer (NSCLC)." (PMID 32983988, 2020). "In addition, in non-small-cell lung cancer, the epidermal growth factor receptor (EGFR) has detected mutations with sensitivities similar to those obtained in plasma." (PMID 32294884, 2020). "The third-generation epidermal growth factor receptor (EGFR) tyrosine kinase inhibitors (TKI) osimertinib is the current standard of care for patients with advanced EGFR-positive non-small cell lung cancer (NSCLC) who acquired T790M mutation after receiving earlier-generation TKIs therapy." (PMID 32067121, 2020). "For instance, autophagy contributes to EGFR inhibitor responses in non-small-cell lung carcinoma cells with active EGFR mutations, and therefore, inhibiting autophagy in patients treated with EGFR TKIs may not benefit their clinical outcomes." (PMID 32251287, 2020). "On a large group of patients with non-small-cell lung cancer, Mezequita investigated the relationship between the intensity of radon exposure and the occurrence of specific types of mutations such as EGFR, BRAF, KRAS and HER2, as well as ALK and ROS1 rearrangements." (PMID 33327615, 2020). "This is just a fraction of the total cfDNA in blood, but this analyte can be analyzed to identify tumor driver mutations that can be therapeutically targeted, such as mutations in epidermal growth factor receptor (EGFR) in non-small cell lung cancer (NSCLC) that are currently used in the clinic." (PMID 32850309, 2020).
non-small cell lung carcinoma (continued). "Osimertinib has demonstrated efficacy against stable or asymptomatic central nervous system (CNS) metastases of epidermal growth factor receptor (EGFR) mutation-positive non-small-cell lung cancer (NSCLC) in phase 2 and 3 clinical trials that allowed prior CNS radiotherapy." (PMID 32257480, 2020). "The molecular diversity associated with oncogenesis between Caucasians and Asians have been established by the identification of EGFR sensitizing mutations in non-small cell lung cancer, wherein EGFR-mutant tumors are more prevalent in Asians than Caucasians (50 vs. 10%)." (PMID 32695676, 2020). "Detection of epidermal growth factor receptor (EGFR) mutations in exons 18–21 is recommended in all patients with advanced Non-small-cell lung carcinoma due to the demonstrated efficiency of the standard therapy with tyrosine kinase inhibitors in EGFR-mutated patients." (PMID 32245434, 2020). "In contrast, the incidence of EGFR mutation is higher in females with non-small cell lung cancers." (PMID 33330090, 2020). "Immunotherapy is less effective in non-small cell lung cancer (NSCLC) with driver mutations in epidermal growth factor receptor (EGFR) or anaplastic lymphoma kinase (ALK) and some may extrapolate this trend to other driver mutations." (PMID 33269152, 2020). "We analyzed the EGFR gene and its landscape (+/- 500,000 base pairs) using this approach and were able to identify a region of non-coding DNA with over 90% similarity to the most common activating EGFR mutation in non-small cell lung cancer." (PMID 31940362, 2020). "In this study, Sel-CapTM, a next-generation sequencing (NGS)-based genotyping platform, showed high sensitivity for detection of epidermal growth factor receptor (EGFR) gene mutations in plasma samples collected from 185 patients with non-small cell lung cancer (NSCLC)." (PMID 33266057, 2020). "al. demonstrated that active EGFR binds to beclin-1, inhibiting its autophagy function in non-small cell lung cancer (NSCLC), and EGFR-mutated NSCLC cells presented improved tumor progression and partial tumor resistance to therapy with tyrosine kinase inhibitors." (PMID 33233671, 2020). "Additionally, EGFR mutations were detected from DNA obtained from EVs in bronchoalveolar lavage fluid (BALF) of non-small-cell lung cancer (NSCLC) patients." (PMID 33007940, 2020). "Moreover, reversal effect of vitamin D has been also observed in a non-small cell lung cancer cell line (HCC827R1 Cells) with epidermal growth factor receptor (EGFR) mutation that made these cells erlotinib-resistant." (PMID 32560347, 2020). "Currently, the use of ctDNA detection in cancer therapy has been approved by the US Food and Drug Administration as a treatment determinant (osimertinib or erlotinib) in non-small-cell lung carcinoma (NSCLC) patients with an EGFR mutation in the event that a tumor biopsy cannot be performed." (PMID 32180799, 2020). "Typically, in current clinical practice, erlotinib is prescribed to advanced non-small cell lung cancer patients with tumors harboring an EGFR sensitizing mutation, due to its higher likelihood of response rate and lower overall toxicity rate relative to cytotoxic chemotherapy." (PMID 32138779, 2020). "The real-world efficacy of epidermal growth factor receptor (EGFR)-tyrosine kinase inhibitors (TKIs) in patients with advanced non-small cell lung cancer (NSCLC) harboring EGFR-activating mutations remains unclear." (PMID 32917914, 2020). "The third-generation tyrosine kinase inhibitor (TKI), osimertinib, has revolutionized the treatment of patients with non-small cell lung carcinoma with epidermal growth factor receptor (EGFR)-activating mutation, and resistant to first- and second-generation TKIs." (PMID 32674434, 2020).
non-small cell lung carcinoma (continued). "The role of ctDNA is now well established in the clinical decision in certain alterations and tumors, such as the epidermal growth factor receptor (EGFR) mutation in non-small cell lung cancer and the v-Ki-ras2 kirsten rat sarcoma viral oncogene homolog (KRAS) mutation in colorectal cancer." (PMID 32010431, 2020). "For example, the use of higher doses of BRAF/MEK inhibitors is an interesting field inspired by studies of a pulsatile schedule of erlotinib evaluated in non-small cell lung cancer patients with brain metastasis and epidermal growth factor receptor (EGFR) mutation." (PMID 32575838, 2020). "However, this subject would need further explorations because the prognostic value of such co-existing genetic alterations has been demonstrated in melanoma and in other cancers (e.g., in non-small cell lung carcinoma harboring activating EGFR mutations)." (PMID 32784823, 2020). "This is also true for non-small cell lung cancer and EGFR mutations." (PMID 31970428, 2020). "Although the inhibitors of singly mutated epidermal growth factor receptor (EGFR) kinase are effective for the treatment of non-small cell lung cancer (NSCLC), their clinical efficacy has been limited due to the emergence of various double and triple EGFR mutants with drug resistance." (PMID 33297461, 2020). "Furthermore, a recent study found that FASN mediates EGFR palmitoylation in EGFR-mutated chemo-resistant non-small cell lung cancer." (PMID 32792852, 2020). "One of the most characteristic examples is EGFR-driven lung adenocarcinoma in non small-cell lung cancer (NSCLC), as there have been cases of resistance associated with conversion to small-cell lung cancer (SCLC) phenotype after long-term treatment with EGFR tyrosine kinase inhibitors." (PMID 31970428, 2020). "Using non-small cell lung cancer as a case study, we show that interaction terms that capture associations between drugs, pathways, and mutant kinases quantitatively contribute to the response of two EGFR inhibitors (afatinib and lapatinib)." (PMID 33183223, 2020). "Quantitative spectral CT parameters may be valuable for reflecting Ki-67 expression and EGFR mutation status in non-small-cell lung cancer (NSCLC)." (PMID 32103127, 2020). "In the randomized phase IIb LUX-Lung 7 trial, afatinib significantly improved progression-free survival (PFS) and time-to-treatment failure vs gefitinib in patients with treatment-naïve epidermal growth factor receptor mutation-positive non-small cell lung cancer." (PMID 30783814, 2019). "Studies have shown that the use of first-order histogram features in radiomics features based on computed tomography (CT) could predict EGFR mutation status in non-small cell lung cancer (NSCLC)." (PMID 31174617, 2019). "According to the statistical analysis of the Catalogue of Somatic Mutation In Cancer (COSMIC) database, the abnormal expression or mutation of EGFR gene exists in almost all solid tumors, and the proportion of EGFR gene mutation in non-small cell lung cancer (NSCLC) patients are up to 26% or more." (PMID 31367332, 2019). "Recent findings suggest that a fraction of EGFR-mutant non-small-cell lung cancers (NSCLC) carry additional driver mutations that could potentially affect the activity of EGFR tyrosine kinase inhibitors (TKIs)." (PMID 30857358, 2019). "Successful applications of Abl inhibitor for BCR-Abl-dependent chronic myeloid leukemia, EGFR inhibitors for EGFR mutation dependent non-small cell lung cancer, and ErbB2 inhibitors for ErbB2-dependnet breast cancer are all examples of both the power of targeted therapy and the challenge it faces." (PMID 30754629, 2019). "Genomic sequencing of tumor DNA has changed the therapeutic landscape for non squamous, non small cell lung cancer (NSCLC) with the discovery of recurrent oncogenic driver mutations in EGFR, ALK, and ROS‐1 that can be specifically and effectively targeted by new drugs." (PMID 30773851, 2019).
non-small cell lung carcinoma (continued). "We compared four well-established and one in-house method for the analysis of the EGFR T790M mutation in plasma cell-free DNA (cfDNA), in hope to find a better way to select non-small cell lung cancer (NSCLC) patients appropriate for 3rd-generation TKI therapy." (PMID 31380273, 2019). "The demonstration of EGFR T790M gene mutation in plasma is crucial to assess the eligibility of Non Small Cell Lung Cancer (NSCLC) patients, who have acquired resistance to first or second generation Tyrosine Kinase Inhibitors (TKIs), to receive a subsequent treatment with osimertinib." (PMID 31029076, 2019). "In our earlier work, we reported highly sensitive detection of EGFR mutations (T790M and L868R) in microfluidically enriched CTCs, which showed a complete concordance of mutation status with matched primary tumors in non-small-cell lung cancer (NSCLC) patients." (PMID 31635038, 2019). "Although third-generation EGFR-TKIs could overcome EGFR mutation threonine 790 (T790M) resistance and are becoming the new first-line standard in EGFR mutant non-small cell lung cancer (NSCLC), acquired resistance is virtually inevitable." (PMID 31747941, 2019). "The first liquid biopsy test approved by the U.S. Food and Drug Administration for a cancer disease is the blood-based companion diagnostic to select patients with non-small cell lung cancer (NSCLC) for treatment with the epidermal growth factor receptor (EGFR) inhibitor, erlotinib." (PMID 30841521, 2019). "Treatment of non-small cell lung cancer (NSCLC) harboring epidermal growth factor receptor (EGFR) activating mutation with EGFR-TKIs has achieved great success, yet faces the development of acquired resistance as the major obstacle to long-term disease remission in the clinic." (PMID 31227004, 2019). "To investigate the exposure–safety relationships of afatinib in Japanese population, we performed population pharmacokinetics (PK) analysis of afatinib in Japanese advanced non-small cell lung cancer patients harboring epidermal growth factor receptor mutation." (PMID 31796841, 2019). "Epidermal growth factor receptor (EGFR) mutational testing in advanced non-small-cell lung cancer (NSCLC) is usually performed in tumor tissue, although cfDNA (cell-free DNA) could be an alternative." (PMID 30809319, 2019). "The purpose of this study was to examine the impact of epidermal growth factor receptor (EGFR) mutation status and tyrosine kinase inhibitors (TKIs) on the survival of brain metastases (BM) in patients with surgically resected non-small cell lung cancer (NSCLC)." (PMID 31048854, 2019). "The discovery of epidermal growth factor receptor (EGFR) mutation in non-small cell lung cancer and other types of cancers and the application of EGFR inhibitor have launched a new era of personalized medicine in patients with advanced non-small cell lung carcinoma (NSCLC)." (PMID 32922901, 2019). "Owing to the well-established beneficial outcomes of clinical trials, epidermal growth factor receptor-tyrosine kinase inhibitors (EGFR-TKIs), have been approved as the standard regimens in patients with non-small cell lung cancer (NSCLC) harboring EGFR sensitive mutations." (PMID 30736738, 2019). "In NSCLC (non-small-cell lung cancer) patients, metformin combined with tyrosine kinase inhibitors (TKIs) could harbor mutations in EGFR (epidermal growth factor receptor) to reduce resistance to TKI and prolong the overall survival of patients." (PMID 30881522, 2019). "In addition, EGFR overexpression is also associated with chemoresistance in non-small-cell lung cancer." (PMID 29983647, 2018). "Most non-small cell lung cancer patients with active epidermal growth factor receptor (EGFR) mutation will eventually acquire drug resistant to EGFR tyrosine kinase inhibitors, such as gefitinib, resulting in disease progression, which involves a variety of complex mechanisms." (PMID 29526180, 2018).
non-small cell lung carcinoma (continued). "Overexpression of EGFR is associated with a poor prognosis in non-small-cell lung cancer." (PMID 29983647, 2018). "In one particular study, a mesenchymal drug-tolerant state has been observed to function as an important intermediate stage, enabling initially-EGFRT790M-negative non-small-cell lung cancer cells to acquire this “gatekeeper” mutation following treatment with EGFR inhibitors." (PMID 30043221, 2018). "In comparison, the younger brother of CTCs, the ctDNA, has already been implemented in routine clinical practice after EMA (European Medicines Agency) approval of the EGFR mutation test (Therascreen EGFR Plasma, Qiagen) in plasma of patients with non-small cell lung cancer (NSCLC)." (PMID 30087246, 2018). "Furthermore, high polysomy or gene mutation has been reported to play a role in EGFR overexpression in non-small-cell lung cancers and in breast cancer." (PMID 29849821, 2018). "L861Q may be a clinically valuable mutation because it is known to sensitize non-small-cell lung cancers to treatment with the second-generation EGFR TKI afatinib in particular." (PMID 30305059, 2018). "Moreover, BIM protein expression is always downregulated in non-small-cell lung cancer carriers of EGFR mutations." (PMID 30518879, 2018). "In this study, cell blocks allowed for the identification of the sub-type of non-small cell lung cancer, provided that the material was suitable for the epidermal growth factor receptor (EGFR) gene mutation analysis, and allowed for the identification of a mutation." (PMID 30344250, 2018). "The EGFR-T790M mutation is clinically detected using re-biopsy in approximately 50% of patients with acquired resistance to epidermal growth factor receptor tyrosine kinase inhibitors (EGFR-TKIs) in advanced non-small cell lung cancer (NSCLC) who harbor EGFR mutations." (PMID 30537950, 2018). "Checkpoint inhibitors in metastatic EGFR-mutated non-small cell lung cancer – a meta-analysis." (PMID 30400822, 2018). "In the present study, we found that CAGE could regulate autophagic flux and responses to anti-cancer drugs in non-small cell lung cancer cells with EGFR mutations such as PC-9/ER cells and H1975 cells." (PMID 30619741, 2018). "EGFR mutations are actionable in non-small cell lung cancer (OncoKB level 1)." (PMID 30442178, 2018). "Actually, complete abrogation of EGFR N-glycosylation by tunicamycin led to increased susceptibility of EGFR to the tyrosine kinase (TK) inhibitor erlotinib, a frequently utilized drug to downregulate EGFR activation supporting constitutive proliferation of non-small cell lung cancer." (PMID 29541627, 2018). "Eligible patients (≥20 years) with stage IIIB/IV or recurrent non-small-cell lung cancer and confirmed activating mutations of EGFR (exon 19 deletion or L858R point mutation in exon 21) received oral erlotinib 150 mg/day until disease progression or unacceptable toxicity." (PMID 27659294, 2017). "Most patients with advanced non-small cell lung carcinoma (NSCLC) with epidermal growth factor receptor (EGFR) activating mutations will develop resistance after 6–9 months of treatment with first generation reversible tyrosine kinase inhibitors (TKIs) such as erlotinib or gefitinib." (PMID 28854272, 2017). "In addition to mutations, overexpression of EGFR was then observed to promote cancer progression, first in carcinomas, and later on in sarcomas, non-small cell lung cancer (NSCLC) and malignant gliomas." (PMID 28513565, 2017). "Approximately 10–30% of non-small cell lung cancer (NSCLC) patients have EGFR gene mutations." (PMID 28219421, 2017). "The most successful examples to date include the use of [11C]erlotinib, which was able to distinguish between sensitizing mutations of EGFR and wild type EGFR in non-small cell lung cancer patients, and [18F]afatinib showing a promising similar preclinical targeting profile in tumor bearing mice." (PMID 28418885, 2017).